ASIC4 (acid sensing ion channel subunit family member 4)
Description:
Does not exhibit measurable stand-alone pH-gated sodium channel activity but may form pH-gated heterotrimeric sodium channels. Its activity could also depend on alternative gating mechanisms.
Synonyms: ACCN4; BNAC4
Tractability: Antibody: UniProt places it where antibodies can reach, with medium confidence; UniProt predicts a signal peptide or a membrane-spanning region; its Gene Ontology location is reachable by antibodies, with medium confidence.
Gene: Protein-coding gene on chromosome 2 (219,514,170 to 219,538,772, forward strand). Ensembl gene ENSG00000072182.
Subcellular location: Cell membrane
Subcellular location (Human Protein Atlas): Golgi apparatus
Pathways (Reactome):
Transport of small molecules: Stimuli-sensing channels
Gene Ontology:
Molecular function: protein binding; ligand-gated sodium channel activity; sodium channel activity
Biological process: sodium ion transmembrane transport; sodium ion transport
Cellular component: plasma membrane; membrane
Genetic constraint (gnomAD): Loss-of-function variants: 28 observed, 55.66 expected, observed/expected ratio (o/e) 0.5, 90% interval 0.37 to 0.69. The upper end of that interval is the gene's LOEUF score, 0.69, which puts it in group 2 of 6, group 1 being the genes least tolerant of losing a copy. Missense variants: 649 observed, 759.72 expected, observed/expected ratio (o/e) 0.85, 90% interval 0.8 to 0.91. Synonymous variants: 289 observed, 314.01 expected, observed/expected ratio (o/e) 0.92, 90% interval 0.83 to 1.01.
Homologues: Orthologues: chimpanzee ASIC4 (99% identical), macaque ASIC4 (98% identical), mouse Asic4 (98% identical), rat Asic4 (97% identical), rabbit ASIC4 (97% identical), guinea pig ASIC4 (96% identical), pig ASIC4 (89% identical), dog ASIC4 (87% identical), tropical clawed frog asic4 (67% identical), zebrafish asic4a (61% identical), zebrafish asic4b (60% identical), Caenorhabditis elegans acd-2 (21% identical), and 23 more. Paralogues in human: ASIC1 (48% identical), ASIC3 (45% identical), ASIC2 (41% identical), SCNN1B (23% identical), SCNN1D (22% identical), SCNN1A (22% identical), ASIC5 (22% identical), SCNN1G (20% identical).
Diseases named in the same sentence as ASIC4 in open-access papers:
ASIC4 is named in the same sentence as 19 diseases in open-access papers, as found by Europe PMC text mining. Sharing a sentence is not in itself a finding about the gene and the disease. The quoted sentences say what the papers report.
Anxiety (3 papers, 2016 to 2025). Intense feelings of nervousness, tension, or panic often arise in response to interpersonal stresses. "Here we combined chemo-optogenetic, conditional knockout, gene rescue, molecular biology and biochemistry, and electrophysiological approaches to probe the roles of ASIC4 and ASIC4-expressing cells in anxiety-associated responses in mouse models." (PMID 40264173, 2025). "This research highlights the significant role of ASIC4 in managing anxiety-related behaviors, emphasizing its interaction with ASIC1a within key brain regions linked to fear and anxiety." (PMID 40264173, 2025). "Conditional knockout of ASIC1a in ASIC4-positive cells reduced anxiety-associated behaviors." (PMID 40264173, 2025). "In brief, the expression of ASIC4 could downregulate ASIC1a channel activity, which is associated with anxiety-like responses." (PMID 40264173, 2025). "By employing advanced chemo-optogenetic and genetic tools, we uncover that activating ASIC4-positive cells enhances anxiety responses, while its absence in specific brain areas leads to anxiety traits." (PMID 40264173, 2025). "Together, these data suggest that ASIC4 plays an important role in fear and anxiety-related behaviors in mice by modulating ASIC1a activity in the amygdala and BNST." (PMID 40264173, 2025). "Because ASIC4 is widely expressed in the central nervous system, we next probed which brain regions were critical for ASIC4’s role in modulating anxiety and fear responses." (PMID 40264173, 2025). "Further, we discover crucial glycosylation sites on ASIC4 that affect ASIC1a's surface expression and functionality, influencing anxiety phenotypes." (PMID 40264173, 2025). "Here we further demonstrated that chemo-optogenetic activation of ASIC4-expressing neurons had a similar effect as conditional ASIC4 KO in the amygdala or BNST in increasing anxiety levels in mice." (PMID 40264173, 2025). "Elevated ASIC1a activity in ASIC4-KO neurons, mainly in the amygdala or BNST, is linked to increased anxiety/fear levels." (PMID 40264173, 2025). "Restoring ASIC4 expression in amygdala neurons rescues deficits in anxiety-like response in ASIC4-KO mice." (PMID 40264173, 2025). "ASIC4-knockout (ASIC4-KO) mice increased anxiety-like behaviors that contrasted with reduced anxiety-like response in ASIC1a-knockout mice." (PMID 40264173, 2025). "Restoring ASIC4 expression in BNST neurons rescues deficits in anxiety-like response in ASIC4-KO mice." (PMID 40264173, 2025). "Previously, we demonstrated that Asic4−/− mice showed increased innate fear responses and anxiety-related behaviors as compared with wild-type mice." (PMID 40264173, 2025). "Chemo-optogenetically activating ASIC4-positive cells induced fear and anxiety-like responses in mice." (PMID 40264173, 2025). "However, how ASIC1a and ASIC4 modulate anxiety-associated responses remains unknown." (PMID 40264173, 2025). "Consistently, Asic4-knockout (Asic4−/−) mice have shown contrasting behavioral phenotypes to ASIC1a in modulating innate fear and anxiety." (PMID 29793480, 2018). "ASIC4 is another key player in regulating anxiety/fear responses." (PMID 40264173, 2025). "Additionally, mutations at N191 and N341 N-glycosylation sites substantially affected ASIC4's ability to reduce acid-induced IASIC1a, amplitude, which heightened anxiety/fear levels." (PMID 40264173, 2025). "We next tested whether restored ASIC4 expression in the BNST could also rescue the anxiety/fear phenotypes of Asic4−/− mice." (PMID 40264173, 2025). "We previously showed that ASIC4 KO enhanced but ASIC1a KO reduced anxiety levels in mice." (PMID 40264173, 2025). "To understand whether activating ASIC4-expressing cells could modulate fear and anxiety responses, we applied chemo-optogenetic approaches by using Asic4CreERT2::LMO3 mice." (PMID 40264173, 2025). "A schematic model of how ASIC4 expression influences ASIC1a activity and anxiety levels." (PMID 40264173, 2025).
Anxiety (continued). "Mice with brain region-specific ASIC4 KO underwent anxiety-related behavior tests." (PMID 40264173, 2025). "In contrast, both conditional KO and gene restoration in Asic4−/− studies discounted a role for hippocampal ASIC4 in innate anxiety, although the hippocampus plays an important role in anxiety and fear memory, and fear extinction requires ASIC1a-dependent regulation of the ventral hippocampus." (PMID 40264173, 2025). "In the present study, we tested whether ASIC4 could modulate ASIC1a activity in the amygdala and BNST, crucial brain regions associated with anxiety and fear, thereby modulating anxiety and fear responses in mice." (PMID 40264173, 2025). "Conditional knockout of ASIC4 in amygdala/BNST affected anxiety/fear responses in mice." (PMID 40264173, 2025). "We tested whether restoration of ASIC4 expression in related brain regions of ASIC4-KO mice could rescue their anxiety/fear phenotypes." (PMID 40264173, 2025). "It has been suggested that ASIC4 plays a modulatory role and can interact with polyubiquitin to downregulate other ASICs and recent evidence suggests that it can counteract the activity of ASIC1a in the brain to modulate fear and anxiety behavior." (PMID 27964758, 2016). "Hence, conditional knockout Asic1a in ASIC4-expressing cells could fully replicate the anxiety phenotypes of Asic1a−/− mice." (PMID 40264173, 2025). "Previous studies have shown that ASIC4 can regulate ASIC1a surface expression in an heterologous expression system, so we wondered whether ASIC4 could modulate ASIC1a activity and thus influence anxiety-like response." (PMID 40264173, 2025). "Also, mice lacking ASIC4 (Asic4−/−) in the amygdala or the bed nucleus of the stria terminalis (BNST) exhibited anxiety-associated phenotypes." (PMID 40264173, 2025). "In this study, we highlighted ASIC4 as an important regulator to extend our understanding of ASIC1a as a key player in the neurocircuitry of the amygdala and BNST in modulating innate anxiety." (PMID 40264173, 2025). "Especially, ASIC1a and ASIC4 of the ASIC family are widely expressed in the central nervous system and their gene knockouts result in reducing or enhancing anxiety-like responses in mice respectively." (PMID 40264173, 2025). "By using chemo-optogenetic, conditional KO, and AAV-driven gene restoration approaches, we successfully demonstrated that ASIC4-expressing cells of the amygdala and BNST play an essential role in modulating innate anxiety and fear responses in mice." (PMID 40264173, 2025). "Combining chemo-optogenetic, conditional ASIC4-KO, electrophysiology, and adeno-associated virus (AAV)-driven gene rescue approaches, we revealed that ASIC1a channel activity in ASIC4-positive cells of the amygdala and BNST plays key roles in regulating anxiety and fear responses." (PMID 40264173, 2025). "Further studies should probe how ASIC1a homomeric and ASIC1a/ASIC4 heteromeric channels differentially contribute to neuronal excitability in response to stress and whether the BLA-FSINs are ASIC4-expressing neurons involved in regulating innate anxiety." (PMID 40264173, 2025). "Therefore, although ASIC4 is widely expressed in the brain, specifically altered ASIC4 expression in the amygdala or BNST may be sufficient for regulating anxiety responses." (PMID 40264173, 2025). "However, as ASIC4 itself does not respond to acidosis, how ASIC4 modulates anxiety and fear responses remains unknown." (PMID 40264173, 2025).
anxiety disorder (1 paper, 2025). A category of psychiatric disorders which are characterized by anxious feelings or fear often accompanied by physical symptoms associated with anxiety. "Understanding the functionality of ASIC1a/ASIC4 heteromeric channels in the amygdala and BNST would bring new insights for the development of new therapeutic strategies for treating anxiety disorders, improving the quality of life for those affected by these conditions." (PMID 40264173, 2025).
breast carcinoma (1 paper, 2017). "We also confirmed the expression of ASIC3 and ASIC4 acid-sensing channels, as well as GPRs in all the mesenchymal cells analyzed, MSCs and osteoblasts, and CAFs that were directly isolated from BM of breast carcinoma." (PMID 28903357, 2017).
cerebral infarction (1 paper, 2025). An ischemic condition of the brain, producing a persistent focal neurological deficit in the area of distribution of the cerebral arteries. "Although the role of Asic4 investigated in our study remains to be clarified, Asic1a has been found to exacerbate infarction by functioning to induce acid-induced neurotoxicity, i.e., neuronal cell death, during cerebral infarction." (PMID 40167862, 2025).
lung adenocarcinoma (1 paper, 2022). A carcinoma that arises from the lung and is characterized by the presence of malignant glandular epithelial cells. "In line, the low expression of the gene coding ASIC1 and the high expression of the gene coding ASIC4 are correlated with better survival prognosis for the patients with lung adenocarcinoma at II–IV stages." (PMID 35837090, 2022). "Bioinformatic analysis of the gene expression in the tissues from the patients with lung adenocarcinoma revealed possible implications of ASIC1, ASIC2, ASIC3, ASIC4, α-ENaC, and γ-ENaC in the disease progression." (PMID 35837090, 2022).
ASIC4 also shares sentences with these, for which no sentence is quoted: lung carcinoma (3 papers); cancer (2); melanoma (2); Acidosis (1); adenocarcinoma (1); bladder cancer (1); glioblastoma (1); head and neck squamous cell carcinoma (1); infarction (1); metastatic melanoma (1); osteoporosis (1); ovarian carcinoma (1); prostate carcinoma (1); tumor (1).